OGFRP1 (opioid growth factor receptor pseudogene 1)
Gene: Long non-coding RNA gene on chromosome 22 (42,269,703 to 42,279,534, forward strand). Ensembl gene ENSG00000182057.
Diseases named in the same sentence as OGFRP1 in open-access papers:
OGFRP1 is named in the same sentence as 14 diseases in open-access papers, as found by Europe PMC text mining. Sharing a sentence is not in itself a finding about the gene and the disease. The quoted sentences say what the papers report.
endometrial cancer (5 papers, 2020 to 2023). Primary or metastatic malignant neoplasm involving the endometrium (mucous membrane that lines the endometrial cavity). "Long noncoding RNAs (lncRNAs) OGFRP1 is up-regulated in endometrial cancer and cervical carcinoma, and OGFRP1 suppression inhibits the malignant behavior of cancer cells." (PMID 34389018, 2021). "OGFRP1 has been studied in liver cancer, endometrial cancer, cervical carcinoma and NSCLC, where it has been found to promote tumor progression." (PMID 33744848, 2021). "LncRNA OGFRP1 promoted the malignant progression of endometrial carcinoma by regulating the miR124-3p/SIRT1 axis and activating the PI3K/AKT/GSK-3β pathway." (PMID 32587476, 2020). "OGFRP1 is found to be up-regulated in endometrial cancer and cervical carcinoma." (PMID 34389018, 2021). "The expression level of OGFRP1 was significantly upregulated in endometrial cancer." (PMID 32185172, 2020). "Furthermore, OGFRP1 suppression inhibits the malignant behavior of the endometrial cancer cells (Ishikawa), hepatocellular carcinoma cells (Hep3B), cervical carcinoma cells (C33A and SiHa), gestational choriocarcinoma cells (JEG3) and human coronary artery endothelial cells (HCAECs)." (PMID 34389018, 2021). "In previous reports, OGFRP1 unregulated the expressions of LYPD3 and SIRT1 by sponging miR-124-3p in NSCLC and endometrial cancer, respectively." (PMID 33744848, 2021).
lung carcinoma (5 papers, 2021 to 2025). "Furthermore, OGFRP1 deficiency reduces tumor growth in animal models, highlighting its potential as a therapeutic target in lung cancer treatment." (PMID 40078365, 2025). "The miR-299-3p/SLC38A1 axis has revealed OGFRP1 as a key regulator of cellular proliferation and ferroptosis in lung cancer." (PMID 40078365, 2025). "Meanwhile, two genes associated with lung cancer, namely, LINC00355 and OGFRP1, were identified by the developed model." (PMID 38710798, 2024). "A significant reduction in lung cancer invasion and migration was observed when OGFRP1 was inhibited." (PMID 37575978, 2023). "OGFRP1 regulates lung cancer cell proliferation and ferroptosis by inhibiting miR-299-3p to enhance SLC38A1 expression." (PMID 36685932, 2022). "We discovered that by inhibiting OGFRP1, the invasion and migration abilities of lung cancer cells could be remarkably hindered." (PMID 37575978, 2023). "Moreover, MS4A1 is dysregulated in asbestos-related lung squamous carcinoma, RAB9B is a target of miR-15/16 which are highly related to lung cancer, LINC00539 is related to tumor immune response while long non-coding RNA, OGFRP1, regulates non-small-cell lung cancer progression." (PMID 33672117, 2021).
gastric cancer (4 papers, 2021 to 2025). A primary or metastatic malignant neoplasm involving the stomach. "LncRNA opioid growth factor receptor pseudogene 1 (OGFRP1) is highly expressed in gastric cancer tissues and cells." (PMID 37569824, 2023). "To verify the results of the bioinformatics analysis, we further detected OGFRP1 expression in 30 cases of gastric cancer." (PMID 33744848, 2021). "OGFRP1 was expressed at abnormally high levels in gastric cancer samples (n = 408) compared to normal samples (n = 211)." (PMID 33744848, 2021). "We used western blot to investigate the pathway by which OGFRP1 knockdown inhibited cell migration in gastric cancer." (PMID 33744848, 2021). "First, we demonstrated that OGFRP1 is highly expressed in gastric cancer by using a bioinformatics analysis." (PMID 33744848, 2021). "In conclusion, we found that lncRNA OGFRP1 was up-regulated in gastric cancer through analysis in both online databases and clinical samples." (PMID 33744848, 2021). "In the present study, we investigated the specific role of lncRNA OGFRP1 on gastric cancer in vitro and in vivo." (PMID 33744848, 2021). "To further confirm the overexpression of OGFRP1, we collected tumor and adjacent tissues of 30 cases with gastric cancer, of which OGFRP1 levels were detected by qPCR." (PMID 33744848, 2021). "To explore more into the mechanisms of OGFRP1 in gastric cancer, we detected the expression and activity in cell groups of key proteins in the key pathway of tumor progression, which is the AKT pathway." (PMID 33744848, 2021). "Consistently, OGFRP1 was proven to be up-regulated in gastric cancer tissues, suggesting its specific role in human gastric cancer." (PMID 33744848, 2021). "Our data demonstrated that suppression of OGFRP1 induced the apoptosis in human gastric cancer cells." (PMID 33744848, 2021). "Our results proved that the suppression of OGFRP1 inhibited the proliferation and migration, and induced cell cycle arrest and apoptosis in gastric cancer cells in vitro." (PMID 33744848, 2021). "In the present study, we demonstrate the abnormally high expression of lncRNA OGFRP1 in gastric cancer tissues for the first time." (PMID 33744848, 2021). "Our results contribute to expanding the knowledge of OGFRP1 functions in promoting tumor progression, as well as provide a potential target for the clinical treatment of human gastric cancer." (PMID 33744848, 2021). "Taken together, these observations demonstrated that the suppression of OGFRP1 regulated the levels of multiple apoptosis-related factors and induced the apoptosis in gastric cancer cells." (PMID 33744848, 2021). "Interference of OGFRP1 markedly blocked cell proliferation and migration, and it induced cell cycle arrest and the apoptosis of gastric cancer cells in vitro." (PMID 33744848, 2021). "In comparison to the paired normal tissues, OGFRP1 level increased significantly in gastric cancer (P<0.05)." (PMID 33744848, 2021). "Taken together, our data suggested that the suppression of OGFRP1 inhibited the migration of gastric cancer cells by reversing the EMT process." (PMID 33744848, 2021). "In the existing research, OGFRP1 was investigated to enhance the growth of gastric cancer cells and inhibit cell death and sensitivity to radiation by controlling the miR-149-5p/MAP3K3 pathway, which has been demonstrated to play a similar role in choriocarcinoma through the miR-4731-5p/HIF3A axis." (PMID 39352634, 2025). "OGFRP1 inhibited the radiosensitivity of gastric cancer by downregulating miR-149-5p." (PMID 37569824, 2023). "Thus, we predicted that the OGFRP1 knockdown blocked the proliferation by inhibiting the activity of the AKT signaling pathway in human gastric cancer cells." (PMID 33744848, 2021). "This proved that the suppression of OGFRP1 inhibited the migration of gastric cancer cells." (PMID 33744848, 2021).
gastric cancer (continued). "Taken together, our results confirmed that OGFRP1 operated as a tumor promotor, and its expression might be posed as a predictor for tumor metastasis of human gastric cancer." (PMID 33744848, 2021). "On GEPIA we analyzed the expression levels of OGFRP1 in gastric cancer." (PMID 33744848, 2021). "To confirm our hypothesis, we knocked down the expression of OGFRP1 in two gastric cancer cell lines, AGS and MKN45." (PMID 33744848, 2021). "Results suggest that OGFRP1 is a potential biomarker and therapeutic target for gastric cancer." (PMID 33744848, 2021). "The in vivo results further confirmed the antitumor effects of OGFRP1 knockdown on gastric cancer." (PMID 33744848, 2021). "OGFRP1 knockdown blocks cell proliferation and migration, and it induces cell cycle arrest and apoptosis by inhibiting the activity of the AKT/mTOR pathway in human gastric cancer." (PMID 33744848, 2021).
non-small cell lung carcinoma (4 papers, 2021 to 2023). A group of at least three distinct histological types of lung cancer, including non-small cell squamous cell carcinoma, adenocarcinoma, and large cell carcinoma. "Here, we evaluated the expression pattern, biological function and potential mechanism of OGFRP1 in non-small cell lung cancer (NSCLC)." (PMID 34389018, 2021).
cervical carcinoma (3 papers, 2021). A carcinoma arising from either the exocervical squamous epithelium or the endocervical glandular epithelium. "Increased expression of OGFRP1 has been reported in cervical cancer with subsequent silencing, resulting in the loss of proliferative and invasive capacities of cervical carcinoma cells." (PMID 34204445, 2021).
prostate carcinoma (3 papers, 2020 to 2023). A carcinoma that arises from epithelial cells of the prostate gland. "OGFRP1 acts as an oncogene to promote the development and progression of many kinds of tumors including lung, colon, gastric, and prostate cancers." (PMID 36605426, 2022). "The correlation between OGFRP1 and clinicopathological characteristics of prostate cancer was analyzed." (PMID 32428870, 2020). "In this research, we found that OGFRP1 was up-regulated in prostate cancer (PCa) clinical samples and cell lines." (PMID 32428870, 2020). "Correlation between OGFRP1 and clinicopathological characteristics of prostate cancer." (PMID 32428870, 2020).
hepatocellular carcinoma (2 papers, 2021). A malignant tumor that arises from hepatocytes. "At the same time, the latest research proves that OGFRP1 can abnormally activate the AKT pathway in hepatocellular carcinoma." (PMID 33744848, 2021).
bladder cancer (1 paper, 2025). "Furthermore, Zhou revealed that OGFRP1 was involved in shaping the profile of tumor-infiltrating B lymphocytes in bladder cancer, indicating its potential significance for prognosis and immunotherapy." (PMID 39352634, 2025).
lung adenocarcinoma (1 paper, 2023). A carcinoma that arises from the lung and is characterized by the presence of malignant glandular epithelial cells. "Finally, the LASSO regression analysis and the Kaplan-Meier method incorporated 5 lncRNAs: AL606489.1, LINC02178, LINC01117, OGFRP1, and AC087588.1, which were found to be strongly associated to OS in lung adenocarcinoma patients." (PMID 36891153, 2023).
tumor (8 papers, 2020 to 2025). "Decreases in tumor volume (104.23±62.27 mm3) and weight (0.1006±0.0488 g) in nude mice were observed during the OGFRP1 interference, as compared with the control group (418.96±211.96 mm3 and 0.2741±0.0769 g)." (PMID 33744848, 2021). "The expression of OGFRP1 significantly increased in tumor tissues, as compared to the normal tissues (gray box)." (PMID 33744848, 2021). "OGFRP1 promoted tumor progression by increasing the activity of the AKT/mTOR pathway or directly interacting with miR-4640-5p." (PMID 34987577, 2021). "Decreases in tumor volume and weight were observed in the OGFRP1 knockdown of nude mice compared with the control group." (PMID 33744848, 2021). "The effects of OGFRP1 knockdown on tumor growth was further investigated in vivo by using a nude mice xenograft model." (PMID 33744848, 2021). "Knockdown of OGFRP1 inhibited the growth of PCa cells, suggesting a promotional effect of OGFRP1 in tumor progression." (PMID 32428870, 2020). "Notably, OGFRP1 exhibited high expression in mast, T, NK, ciliated and plasma cells of Tumor, while LINC00996 was prominently expressed in macrophage, NK and B cells of Normal." (PMID 39352634, 2025). "Recent studies have demonstrated that lncRNA OGFRP1 may promote tumor progression by regulating metabolism or mediating endothelial–mesenchymal transition in tumors of the digestive system and female reproductive system." (PMID 35754800, 2022). "OGFRP1 promotes tumor progression through activating the AKT/mTOR pathway." (PMID 33744848, 2021). "Additionally, the OGFRP1 inhibition group exhibited decreased expression of PCNA in tumor tissues." (PMID 39352634, 2025). "Therefore, we speculate that OGFRP1 may participate in tumor progression by regulating this pathway." (PMID 33744848, 2021). "CTD-2066L21.3, LINC00355, CTD-2555C10.3, OGFRP1, and LINC00862 were found to be substantially expressed in tumor cells but expressed at low levels in normal cells." (PMID 38710798, 2024).
cancer (3 papers, 2021 to 2024). A tumor composed of atypical neoplastic, often pleomorphic cells that invade other tissues. "Experimental interventions validate that inhibiting LncRNA OGFRP1 could significantly decrease disulfidptosis of cancer cells and further reduces the invasion and migration capabilities of lung cancer." (PMID 38910181, 2024). "The other three were lncRNA OGFRP1, LINC00942, and WWC2-AS2, which were both reported in the field of malignant tumors." (PMID 34987577, 2021).
colorectal (1 paper, 2025). "Recently, it has been shown that lncRNA OGFRP1 mediates the formation of CTCF by means of miR-423-5p, which in turn promotes colorectal carcinogenesis, metastasis, and angiogenesis." (PMID 41502505, 2025).
OGFRP1 also shares sentences with these, for which no sentence is quoted: choriocarcinoma (1 paper); liver cancer (1).